PTH (parathyroid hormone)
Diseases named in the same sentence as PTH in open-access papers (continued):
Sharing a sentence is not in itself a finding about the gene and the disease.
Hypocalcemia (continued). "Although both serum PTH and ALP presented as significant factors for the occurrence of hypocalcemia, ALP’s effects on hypocalcemia occurrence was significant (P < 0.05) compared to PTH’s effects (P > 0.05)." (PMID 32277134, 2020). "This pathological condition is referred to as “post-surgical hypoparathyroidism” (PSHP) and characterized by decreased levels of parathyroid hormone (PTH) in the blood, the development of hypocalcemia and hyperphosphatemia." (PMID 34513060, 2020). "Laboratory data showed hypocalcemia, hypophosphataemia, low serum 1,25-(OH)2D3 level, normal serum phosphorus, elevated ALP, 25-(OH)D3 and PTH levels." (PMID 33004071, 2020). "Laboratory tests showed hypocalcemia, hypophosphatemia, phosphaturia, and raised serum ALP and PTH levels with normal vitamin D levels." (PMID 32926064, 2020). "Laboratory tests showed hypocalcaemia, hypophosphataemia, high levels of serum ALP, PTH and 25-(OH) D3, and low serum 1, 25-(OH)2D3 level." (PMID 33004071, 2020). "Furthermore, PTH-resistance in PHP1B may remain undetected until symptomatic hypocalcemia develops." (PMID 32318528, 2020). "Secretion of fibroblast growth factor 23 (FGF23) and parathyroid hormone (PTH) are increased to prevent accumulation of P and hypocalcaemia." (PMID 33374582, 2020). "Hypocalcemia is common in CKD patients and contributes to increased PTH secretion and abnormal bone remodeling." (PMID 32961953, 2020). "However, postoperative serum PTH levels in patients with vitamin D deficiency may be even higher than in those without vitamin D deficiency, despite the higher risk of hypocalcemia in the first group of patients." (PMID 31340251, 2019). "Enhanced PTH release occurs in response to hypocalcemia, hyperphosphatemia, and low 1,25(OH)2D level, whereas high serum levels of calcium, 1,25(OH)2D, or FGF23 suppress PTH production." (PMID 31637056, 2019). "Typical laboratory findings are hypocalcaemia, elevated serum levels of alkaline phosphatase (ALP) and of PTH with low or normal levels of 1,25-OH2D despite normal or increased concentrations of 25-OHD." (PMID 30282619, 2019). "Calcium homeostasis is maintained by parathyroid hormone (PTH) and vitamin D. Approximately 33% of GD patients treated with ERT experience temporary hypocalcaemia 10 to 12 days after the start of the treatment." (PMID 31791361, 2019). "Although hypocalcemia is one of the hallmarks of PHP1A, our patient had normocalcemia, a high-to-normal phosphate level, and an elevated PTH level, which is similar to several other cases." (PMID 30060753, 2018). "The primary role of parathyroid hormone (PTH) is to prevent and reverse acute hypocalcemia by mobilizing calcium from bone, stimulating renal Ca2+ reabsorption, and by promoting the production of the active vitamin D metabolite calcitriol." (PMID 29063159, 2018). "Similar to cases of nutritional rickets, typical cases with VDDR1A present with hypocalcemia, hypophosphatemia and increased serum levels of alkaline phosphatase (ALP) and PTH." (PMID 29280738, 2017). "Skeletal deformities compatible with rickets, hypocalcemia, hypophosphatemia, markedly elevated ALP and PTH, normal 1,25(OH)2D and low 25(OH)D levels were present." (PMID 29280738, 2017). "Therefore, our conclusion that the accuracy of postoperative PTH to predict post-thyroidectomy hypocalcemia is not affected by vitamin D deficiency may be attributed to the absence of secondary hyperparathyroidism in this study." (PMID 28955671, 2017). "However, preoperative VDD might lead to secondary hyperparathyroidism and an increased bone turnover, subsequently leading to an increased PTH level, which would affect the accuracy of postoperative PTH in predicting postoperative hypocalcemia, but other studies didn't confirm this influence." (PMID 29100453, 2017). "Hypocalcemia, hypophosphatemia, increased serum levels of ALP and PTH, and normal serum levels of 25(OH)D are usually found." (PMID 29280738, 2017).
Hypocalcemia (continued). "In all cases, hypocalcemia, hypophosphatemia, decreased 25(OH)D, markedly elevated ALP and PTH are present." (PMID 29280738, 2017). "PHP type I (PHP1A and PHP1B) patients are characterized by end-organ resistance to the action of the parathyroid hormone (PTH), which leads to hypocalcemia, hyperphosphatemia, and elevated levels of PTH in the absence of vitamin D deficiency." (PMID 26819647, 2016). "In fact hypocalcemia, hyperphosphatemia, or reduction in serum fibroblast growth factor 23 (FGF23) results in increased production of PTH that stimulates hydroxylation of 25(OH)D." (PMID 25161666, 2014). "It regulates its own catabolism via induction of the 24-hydroxylase CYP24A1 and its own metabolism through negative regulation of parathyroid hormone (PTH), which induces CYP27B1 in response to hypocalcaemia." (PMID 25101194, 2014). "Klotho is expressed in parathyroid chief cells and reported to facilitate PTH secretion during hypocalcemia and mediate FGF23 suppression of PTH synthesis and secretion." (PMID 24348262, 2013). "In the parathyroid glands, hypocalcemia seen in elderly CKD patients diminishes CSR signaling and releases CSR-mediated PTH inhibition, thereby enhancing PTH synthesis and secretion and promoting parathyroid hyperplasia." (PMID 23760058, 2013). "Low dietary K+ induced hypocalcemia and changes in PTH were absent in mice with constitutively active NCC, supporting its role in mediating low K+ effects on Ca2+ homeostasis." (PMID 41569700, 2026). "Many studies analyzing BMI impact on surgical outcomes, referred only to hypocalcaemia and Calcium/vitamin D supplementation without taking into account parathyroid hormone levels." (PMID 40616044, 2025). "These achieved partial potassium normalization in three patients (Cases 1, 2, and 5) but failed to correct hypocalcemia or normalize PTH, with symptom recurrence in all three patients upon dose reduction." (PMID 40893942, 2025). "Fluctuations in PTH and mineral metabolism pre-/post-transplant warrant vigilance; symptomatic PFBC is rare, but metabolic Fahr may flare with severe hypocalcemia." (PMID 41531582, 2025). "Statement 1: Biochemical postoperative hypoparathyroidism is defined by an undetectable or low PTH (less than the lower limit of the centre-specific reference range) with or without hypocalcaemia." (PMID 41229353, 2025). "On the other hand, hypoparathyroidism (HypoPTH) is characterized by absent or inappropriately low PTH levels in the presence of hypocalcemia, and it mainly occurs as a neck surgery complication." (PMID 40177730, 2025). "Unlike PHPT, in secondary hyperparathyroidism (SHPT), excessive PTH is not autonomously produced by parathyroid glands, but most commonly results from defects in calcium homeostasis that lead to hypocalcemia." (PMID 40177730, 2025). "Patients with PHP2 demonstrate functioning Gsα and cAMP but do not have phosphaturia secondary to PTH; therefore, the suspected dysfunction resulting in hypocalcemia is thought to be further downstream of the GPCR." (PMID 41181744, 2025). "PHP and PPHP have identical characteristics, but patients with PHP do not respond to PTH and have hypocalcemia, while patients with PPHP have normal serum calcium levels." (PMID 40291321, 2025). "For the purpose of evaluating BGC, the immediate clinical priority is correction of symptomatic hypocalcemia, hyperphosphatemia, and hypomagnesemia and avoidance of iatrogenic extremes of PTH, rather than pursuit of a specific PTH numeric endpoint." (PMID 41531582, 2025). "This process leads to hypoparathyroidism with secondary hypocalcemia, low serum magnesium levels, elevated serum phosphorus, and absent or inappropriately low levels of PTH." (PMID 41480351, 2025). "As described by Goff, reduced PTH secretion in the absence of hypocalcemia limits urinary and salivary P losses while maintaining intestinal absorption and homeostatic balance." (PMID 41295670, 2025).
Hypocalcemia (continued). "Hypoparathyroidism (HypoPT) is characterized by the presence of hypocalcemia resulting from insufficient or absent secretion of PTH from the parathyroid glands." (PMID 40709359, 2025). "Without PTH, calcium mobilization from bone is impaired, leading to hypocalcemia and hyperphosphatemia." (PMID 41211056, 2025). "It is also noted that other covariates such as estimated glomerular filtration rate, vitamin D, or PTH were similar between treatment groups, and in women with and without hypocalcemia (data not shown)." (PMID 39243386, 2025). "Although PTH levels rose on day 4, baseline values were normal, suggesting a transient, compensatory response to hypocalcemia rather than a chronic elevation contributing to sustained phosphaturia." (PMID 41467127, 2025). "Calcium and vitamin D supplementation is very important, whereas active vitamin D analogs should be administered in cases of progressive increases of PTH, regardless of the presence of hypocalcemia." (PMID 40177730, 2025). "Conventional hypoparathyroidism therapy with active vitamin D and calcium addresses hypocalcemia but fails to restore normal PTH physiology." (PMID 40143070, 2025). "These values indicate the likelihood of hypoparathyroidism in patients with hypocalcemia (LR+) and the likelihood of normal PTH levels in patients without hypocalcemia." (PMID 40091995, 2025). "Hypoparathyroidism (HypoPT) is a rare endocrine disease characterized by hypocalcemia, hyperphosphatemia, and insufficient or no parathyroid hormone (PTH) secretion." (PMID 40713713, 2025). "Conventional therapy for hypoparathyroidism aims to alleviate symptoms of hypocalcemia but does not address insufficient parathyroid hormone (PTH) levels." (PMID 39376010, 2025). "We identified high level of preoperative PTH and ALP, low level of preoperative serum calcium, and non-prophylactic intravenous calcium supplementation as risk factors for severe postoperative hypocalcemia." (PMID 41367906, 2025). "Conventional therapy for hypoparathyroidism (active vitamin D and calcium), targets hypocalcemia but does not restore the physiological effects of PTH on bone." (PMID 39376010, 2025). "Hypoparathyroidism (HypoPT) is an endocrine disorder characterized by decreased secretion of parathyroid hormone (PTH) and the biochemical constellation of hypocalcemia and hyperphosphatemia, reduced levels of active vitamin D (1,25-OH2 vitamin D), and hypercalciuria." (PMID 40794165, 2025). "They share several characteristics with mice lacking Vasn, including hypocalcemia and high PTH levels as well as reduced bone formation/turnover." (PMID 39157725, 2024). "Before surgery, patients’ serum PTH and calcium levels were normal, with no patients having hoarseness of voice or hypocalcemia symptoms." (PMID 39687816, 2024). "On the other hand, although the muscle is particularly affected by hypocalcemia due to the lack of PTH, the effects of hypoparathyroidism at the muscle level are less known and characterized." (PMID 37819413, 2024). "In this report, perioperative drop in PTH was not different from a single postoperative PTH value in its ability to predict transient hypocalcaemia and long-term hypoparathyroidism." (PMID 38478048, 2024). "Although, patient CA0159 had hypophosphatemia and high PTH levels, it does not present the typical characteristics of the disease such as rickets, alopecia, cutaneous cysts, or hypocalcemia." (PMID 38586466, 2024). "Transient or temporary hypoparathyroidism can be defined as an undetectable or inappropriately low postoperative PTH level (<10 pg/mL) in the context of hypocalcaemia, with or without hypocalcaemia symptoms." (PMID 39649119, 2024). "Hypoparathyroidism is a disease of inadequately low or absent circulating concentration of PTH that results in hypocalcemia and hyperphosphatemia." (PMID 38562130, 2024).
Hypocalcemia (continued). "Persistently elevated levels of PTH (>800–1000 pg/mL in the absence of hypocalcemia) that fail to respond to a combination of calcimimetics and vitamin D analogues for more than 6–12 months are generally accepted as an indication for PTx." (PMID 38893652, 2024). "This supports that PTH released by the parathyroid gland does not sustain in peripheral circulation, leading to decompensated hypocalcemia." (PMID 39355148, 2024). "The absence of PTH in individuals with HypoPT leads to a significant change in calcium homeostasis, exposing them to the risks of hypocalcaemia, hypercalciuria, hyperphosphatemia, and the abnormal mineralization of the skeletal structure." (PMID 38392648, 2024). "These individuals did not have postoperative permanent hypocalcemia or permanent low PTH, because they had hemithyroidectomy and two or more parathyroid glands retained." (PMID 38431572, 2024). "The activity of 1α-hydroxylase (CYP27B1) and/or 24-hydroxylase (CYP24) is increased by parathyroid hormone (PTH), PTH-related peptide (PTHrP), prostaglandins, hypocalcaemia and hypophosphataemia, and inhibited by fibroblast growth factor-23 (FGF23) and by 1,25(OH)2D alone." (PMID 36835987, 2023). "Parathyroid hormone which is measured at 4 hour post operatively (< 15 pg/mL) and change in PTH after total and near total thyroidectomy accurately predicts post-operative hypocalcemia." (PMID 37636752, 2023). "Nevertheless, a recently identified point mutation in amino acid 25 of the PTHrP signaling homologue PTH (PTHR25C) is responsible for a lack of calcium responsiveness between PTH and its receptor, causing severe hypocalcemia." (PMID 37371129, 2023). "Serum PTH concentrations of <75 pg./mL were highly unlikely to result in hypocalcaemia post‐parathyroidectomy with a sensitivity of 96.6% and specificity of 40.4% (ROC curve was 0.79 (95% CI 0.68–0.89))." (PMID 38053473, 2023). "After undergoing PTX, the PTH levels in SHPT patients drop suddenly, they undergo physiological changes, bone mineralization increases, and calcium in the blood gets redistributed, often accompanied by severe hypocalcemia." (PMID 37250421, 2023). "Preoperative calcium and postoperative PTH levels in people having hypocalcaemia where significantly less compared to the patients having normal calcium." (PMID 37636752, 2023). "Conventional therapy for hypoparathyroidism consisting of active vitamin D and calcium aims to alleviate hypocalcemia but fails to restore normal parathyroid hormone (PTH) physiology." (PMID 36271471, 2023). "There is, however, no firm accepted definition of an inappropriately low PTH level in the face of hypocalcaemia." (PMID 37758507, 2023). "Laboratory tests were consistent with PHP, showing hypocalcemia with elevated PTH, and negative for hyperaldosteronism." (PMID 38045865, 2023). "In contrast, the other three cases were likely to have PHP1b because they presented hypocalcemia, hyperphosphatemia, and increased PTH but without AHO features." (PMID 35992960, 2022). "Conventional therapy for chronic hypoparathyroidism consists of oral calcium supplements and active vitamin D, which can correct hypocalcemia but does not replace other physiologic functions of PTH." (PMID 36389126, 2022). "We found that PTH, Ca, and ALP were predictors of hypocalcemia following PTX in patients with SHPT." (PMID 36531501, 2022). "When PTH levels are inappropriately low or absent, hypocalcemia and hyperphosphatemia frequently ensue." (PMID 36389126, 2022). "PH can be defined as an undetectable or inappropriately low postoperative PTH level in the context of hypocalcaemia with or without hypocalcaemic symptoms." (PMID 36050906, 2022). "Thus, hypocalcaemia, which results from hyperphosphataemia and diminished 1,25(OH)2D3 synthesis in CKD, disables the parathyroid CaSR, elevating PTH secretion." (PMID 36267284, 2022).
Hypocalcemia (continued). "PH is best defined as an undetectable or inappropriately low postoperative PTH level in the context of hypocalcaemia with or without hypocalcaemic symptoms." (PMID 36050906, 2022). "In contrast, Del Rio, in the largest published series of patients undergoing post-thyroidectomy PTH measurement, reported that only 49 of 101 patients developing symptomatic hypocalcaemia were identified by below normal POD1 PTH levels, prompting the authors to abandon postoperative PTH measurement." (PMID 35247092, 2022). "The possibility of a direct effect of SARS-CoV-2 effect on the calcium-vitamin D-parathyroid hormone axis cannot be ruled out, requiring large-scale prospective studies to clarify the mechanisms responsible for hypocalcemia in COVID-19." (PMID 35663648, 2022). "Moreover, in response to the hypocalcemia in the UPF + CSD group, PTH levels were elevated to 2584.02 pg/mL compared to a level of 581.2 pg/mL in the Control group." (PMID 35055025, 2022). "Hypoparathyroidism is a rare endocrine disease characterized by hypocalcemia due to absent or inappropriately low serum parathyroid hormone (PTH) levels." (PMID 35250859, 2022). "With the accurate prediction of hypocalcemia by ICGA, some studies have demonstrated that the systematic measurement of calcium and PTH level and the systematic supplementation of calcium and vitamin D therapy can be omitted in patients with at least one well vascular gland." (PMID 35813620, 2022). "PHP1b is characterized by PTH resistance, hypocalcemia, and hyperphosphatemia, without the addition of AHO-like symptoms." (PMID 35296306, 2022). "Remarkably, the PT-Dicer−/− mice failed to increase serum PTH after the stimuli of acute and chronic hypocalcemia." (PMID 35208186, 2022). "The patient felt much better, did not require oxygen, spoke in full sentences, her vitals were stable, the wound was clean and dry, and calcium and PTH levels were normal, with no symptoms of hypocalcemia." (PMID 35792407, 2022). "The authors concluded that a PTH level less than 10 pg/mL (1.06 pmol/L) on postoperative day one had a sensitivity of 86% and a negative predictive value of 90% for symptomatic hypocalcemia." (PMID 35566513, 2022). "In one family, the diagnosis of iPPSD3 was based on the lack of AHO manifestations together with PTH resistance (hypocalcaemia with increased serum PTH levels) and molecular confirmation." (PMID 36213284, 2022). "Patients with asymptomatic hypocalcemia should not be treated with supplemental calcium, because the hypocalcemia stimulates the stunned parathyroid glands to produce PTH." (PMID 36561510, 2022). "Other authors reported on percentage decrease in PTH values rather than absolute levels, and/or used biochemical rather than symptomatic hypocalcaemia as the main outcome measure, and so it is difficult to draw comparisons between our study and theirs." (PMID 35247092, 2022). "Taking all these considerations into account, the following definition is suggested: PH can be defined as an undetectable or inappropriately low postoperative PTH level in the context of hypocalcaemia with or without hypocalcaemic symptoms." (PMID 36050906, 2022). "Patients with BMI <30 tended to have significantly higher post-operative PTH values than patients with BMI >30 (40.13 pg/ml vs. 27.52 pg/ml, p=0.034), but the incidence of post-operative hypocalcemia was not significantly affected by body weight (p=0.477)." (PMID 33868401, 2021). "It is important to note that profound hypomagnesemia suppresses (rather than stimulates) PTH secretion and increases PTH resistance in the bone leading to hypocalcemia." (PMID 33542868, 2021). "Patients with PHP type II present with hypocalcaemia, decreased serum 1,25(OH)2D3, reduced or absent phosphaturic response to exogenous PTH, and a normal increase in urinary cAMP excretion." (PMID 34068220, 2021).